ACE (angiotensin I converting enzyme)
Diseases named in the same sentence as ACE in open-access papers (continued):
Sharing a sentence is not in itself a finding about the gene and the disease.
myocardial infarction (continued). "Similarly, nanoparticles loaded with cardioprotective drugs, such as statins or angiotensin-converting enzyme (ACE) inhibitors, can target ischemic myocardial tissue to limit infarct size and preserve cardiac function following a heart attack." (PMID 40110293, 2025). "Our results do not provide evidence to support the recommendation to use ACE inhibitors routinely in the treatment of low-risk individuals under the age of 75 years with myocardial infarction and preserved LVEF." (PMID 40886074, 2025). "Additionally, ACE inhibitors help prevent the remodeling of the heart and blood vessels, which can occur after a heart attack or in chronic hypertension, thereby improving long-term cardiovascular outcomes." (PMID 39273041, 2024). "Following myocardial infarction and stroke, we generally observed little change in the proportion of patients with kidney failure prescribed beta-blockers, statins, and ACE inhibitors, perhaps partly explaining why outcomes remain poorer compared with the general population." (PMID 38426727, 2024). "One week of Clofibrate treatment reduced angiotensin II and the angiotensin-converting enzyme, AT1, while bradykinin, ACE-2, and AT2 receptors were elevated, nitric oxide levels increased, and fibrosis and structural damage caused by myocardial infarction improved." (PMID 38764052, 2024). "A comprehensivemeta-analysis of large, randomized placebo-controlled trials including~100,000 patients highlighted beneficial effects ofangiotensin converting enzyme (ACE)-inhibitors on long-term survival with 85% of the effect within the firstseven days after myocardial infarction." (PMID 39077412, 2023). "In this extensive meta-analysis, our objective was to provide insights into the comparative outcomes of administering sacubitril/valsartan versus ACE inhibitors (ACEIs) or angiotensin receptor blockers (ARBs) to individuals who have suffered from acute myocardial infarction (MI)." (PMID 37933369, 2023). "This method of silencing the ACE gene could completely block the effect of ACE after myocardial infarction compared with lowering Ang II (Human angiotension II) level with ACE inhibitor." (PMID 35877508, 2022). "Furthermore, predisposition to stroke, myocardial infarction (MI), or coronary artery disease was correlated with human platelet antigen (HPA-1) 1a/b polymorphisms, whereas MI was further associated with mutations linked to the gene that codes the angiotensin-converting enzyme (ACE)." (PMID 36289926, 2022). "For example, while ACE inhibitors reduce total mortality and risk of myocardial infarction in hypertensives, ARBs do not reduce the risk of either of these outcomes." (PMID 35235571, 2022). "PH: pulmonary hypertension, SD: standard deviation, CAD: coronary artery disease, CVA: cerebrovascular accident, MI: myocardial infarction, NYHA: New York Heart Association, MR: mitral regurgitation, TR: tricuspid regurgitation, ACE: angiotensin-converting enzyme." (PMID 35003943, 2021). "The positive findings for ACE inhibitors and beta blockers complement the established literature for these drugs in chronic heart failure, most of which comes from their use after myocardial infarction." (PMID 31673885, 2019). "The study aims to examine the effects of coenzyme Q10, (a bioenergetic antioxidant), on the indexes of left ventricular remodeling, oxidative damage, and angiotensin-converting enzyme (ACE) level after acute myocardial infarction (AMI) with left ventricular dysfunction." (PMID 30044377, 2018). "The ACE inhibitors are primarily used in patients with CAD following myocardial infarction, in diabetic patients and patients with left ventricular dysfunction but all other patients with CAD should also receive ACE inhibitors once beta-blocker therapy has been established." (PMID 28913755, 2017).
myocardial infarction (continued). "Our findings also suggest that no RAS blocker strategy was superior to ACE inhibitor with respect to all-cause mortality, cardiovascular mortality, myocardial infarction, ESRD, or doubling of serum creatinine." (PMID 26954482, 2016). "Evidence from clinical studies indicate enhanced chymase activity relative to other Ang II forming enzymes including ACE and cathapsin G in the myocardium 14–21 days post myocardial infarction (MI) suggesting the importance of chymase in post ischemic damage to cardiomyocytes." (PMID 27814397, 2016). "Furthermore, standard pharmacological therapies known to modulate inflammatory processes, such as statins and ACE inhibitors, improve heart function in experimental myocardial infarction by cell-therapy similar mechanisms." (PMID 32309541, 2014). "A German analysis evaluated that 47% of men and 59% of women received prescriptions for at least three of the four recommended drugs (antiplatelet drugs, β-blockers, ACE inhibitors, lipid-lowering agents) during the time between the initial myocardial infarction and a secondary event." (PMID 28352428, 2013). "In patients with coronary artery disease angiotensin-converting enzyme (ACE) inhibitors reduce cardiovascular mortality and myocardial infarction rate, most probably by producing beneficial action on functionally damaged endothelial cells and by reversing atherosclerotic process to some point." (PMID 23509696, 2013). "Nevertheless, ACE DD genotype in Tunisians is associated with higher ACE activity and might become a useful clinical marker for CAD risk assessment of acute myocardial infarction." (PMID 22536488, 2012). "Since ACE-inhibitors have similar effects on angiotensin II concentration and recent meta-analysis suggest that there is an increase in the risk of myocardial infarction, rosiglitazone was not investigated in this study." (PMID 22853195, 2012). "In the large scale GenHAT study including data on 37,000 people, the ACE I/D polymorphism did not significantly predict fatal and nonfatal coronary heart disease, myocardial infarction, stroke or all-cause mortality." (PMID 23049672, 2011). "In addition, ACE-inhibitors significantly decrease PAI-1 activity in patients with a myocardial infarction, in hypertensive subjects, and in postmenopausal women." (PMID 20856803, 2010). "Both the ACE DD genotype and the PAI-1 4G allele are associated with increased PAI-1 levels, which promotes thrombosis and is a known risk factor for myocardial infarction." (PMID 20856803, 2010). "Treatment with angiotensin converting enzyme (ACE) inhibitors induces accumulation of bradykinin, reduces plasma angiotensin II levels and decreases plasma plasminogen activator inhibitor-1 (PAI-1), a risk factor for myocardial infarction." (PMID 19936199, 2008). "It is believed that the mechanism of NAC action in myocardial infarction and HF relies on ROS inhibition, antiplatelet, anti-inflammatory, and anti-apoptotic activity, reduction in obesity-related cardiac insulin resistance, as well as inhibition of angiotensin-converting enzyme (ACE)." (PMID 41149623, 2025). "The Antihypertensive and Lipid-Lowering Treatment to Prevent Heart Attack Trial (ALLHAT) aimed to determine whether a CCB (amlodipine) or an ACE inhibitor (lisinopril) lowers coronary heart disease (CHD) or other cardiovascular events compared with a thiazide-like diuretic (chlorthalidone)." (PMID 41234923, 2025). "Therefore, combined chymase and ACE inhibition, compared to ACE inhibition alone, achieved better results in left ventricular function improvement, amelioration of adverse cardiac remodeling, and improvement of survival after myocardial infarction in hamsters." (PMID 38392268, 2024). "These two actions make ACE inhibition a principal target in the treatment of hypertension, myocardial infarction (MI), heart failure, and type I diabetic nephropathy." (PMID 37511409, 2023).
myocardial infarction (continued). "There is controversy related to the role of the ACE D/I polymorphism in the risk of CAD and myocardial infarction (MI)." (PMID 35741131, 2022). "Previously, it was observed that patients who survived a myocardial infarction (MI) had greater plasma ACE levels." (PMID 36110446, 2022). "Currently, most patients with a recent or remote history of myocardial infarction (MI) or HF commonly treat with diuretics, neurohormonal antagonists, β-blockers, and ACE inhibitors." (PMID 31031629, 2019). "Additionally, a recent European guideline evaluation by the EUROASPIRE IV Study Group showed comparable secondary prevention rates at a median follow-up time of 16 months after myocardial infarction: 94% antiplatelets, 86% statins, 83% beta-blockers and 75% ACE inhibitors/AT2 antagonists." (PMID 29119544, 2018). "In conclusion this study identifies a previously undiscovered role ACE and chymase induced synthesis of endogenous Ang II in mediating I/R cardiac injury and highlights the significance of ACE and chymase blockage as a potential therapeutic target in the treatment of myocardial infarction." (PMID 27814397, 2016). "However, several reports suggested that the plasma ACE activity might be higher in adults with several cardiovascular disorders such as myocardial infarction, diabetic nephropathy, and carotid artery thickening." (PMID 24098401, 2013). "Finally, the use of the ACE inhibitor ramipril in the heart outcomes prevention evaluation (HOPE) trial resulted in areduction in all-cause and cardiovascular mortality as well as cardiovascular events, including myocardial infarction and stroke." (PMID 23316345, 2012). "Accordingly, ACE inhibition has been shown to prevent cardiac remodelling after myocardial infarction (MI) and preserves cardiac function." (PMID 22523556, 2012). "Over-expression of ACE2 and inhibition of ACE exert a protective influence on the heart post-myocardial infarction (MI) and prevent the pathological remodelling." (PMID 22523556, 2012). "Additionally, antithrombotic therapy with aspirin or P2Y12 inhibitors, beta‐blockers, ACE inhibitors, or ARBs is recommended for specific clinical profiles, such as those with a history of myocardial infarction (MI), heart failure or hypertension." (PMID 39803729, 2025). "The current management of MINOCA patients typically involves the administration of standard therapy for myocardial infarction with obstructive CAD, such as antiplatelet agents, beta-blockers, and angiotensin-converting enzyme (ACE) inhibitors." (PMID 37834842, 2023). "On the other hand, blocking angiotensin II formation by angiotensin-converting enzyme (ACE) inhibitors can inhibit atherogenesis and prevent cardiovascular events (e.g., myocardial infarction, stroke and cardiovascular mortality)." (PMID 36835270, 2023). "Another study concluded that the adjusted relative risk of the D allele was 1.07 for ischemic heart disease and 1.05 for myocardial infarction, so the ACE genotype does not significantly increase the risk of ischemic heart diseases (IHD) or MI." (PMID 33907634, 2021). "Clinical trials showed that the intake of anti-platelet agents, statins, ACE-inhibitors, and β-blockers lower the risk of death after myocardial infarction, which could not be shown in our analyses as we had a mainly negative association of PDC rates and death." (PMID 32006188, 2020). "Indeed, the authors claimed that although both drugs lower blood pressure, ACE inhibitors but not ARBs may also produce a pressure independent benefit and reduce the risk of myocardial infarction in people with cardiovascular risk factors." (PMID 29545754, 2018). "Inhibition of ACE or blockade of AT1R reduced apoptosis and inhibited myocardial remodeling after myocardial infarction in pigs." (PMID 26569234, 2015). "Both ACE-inhibition and ARB therapy post myocardial infarction have been demonstrated in both animals and humans to prolong survival." (PMID 19357768, 2009).
myocardial infarction (continued). "The Antihypertensive and Lipid‐Lowering Treatment to Prevent Heart Attack Trial (ALLHAT) found that angiotensin‐converting enzyme (ACE) inhibitors, CCBs, and alpha‐receptor blockers were not superior to thiazide diuretics in lowering blood pressure." (PMID 39835349, 2025). "The composite outcomes of cardiovascular mortality, non-fatal myocardial infarction, or stroke occurred in 1599 (10.7%) of the patients allocated ACE inhibitor and in 1910 (12.8%) of those allocated placebo (odds ratio, 0.82; 95% CIs 0.76–0.88; P < 0.0001)." (PMID 34533690, 2023). "In HF patients who experience myocardial infarction (MI), a lower incidence in SCD may contribute to a greater degree to the mortality benefits of ACE inhibition." (PMID 37895150, 2023). "Furthermore, in acute myocardial infarction (AMI), rapid blood flow restoration and post-infarct treatment supported by dual antiplatelet medication, ß-blockers, and angiotensin-converting enzyme (ACE) inhibitors lead to better outcomes." (PMID 35845058, 2022). "Separately, the use of ACE inhibitor or ARB after primary PCI represented a uniquely negative predictor of large myocardial infarct (OR 0.50; 95% CI 0.26–0.97; P = 0.040)." (PMID 30735561, 2019). "BMI: body mass index; MI: myocardial infarction; PCI: percutaneous coronary intervention; LP(a): lipoprotein(a); Lg: logarithm; HDL: high-density lipoprotein; LDL: low-density-lipoprotein; ACE-Is: angiotensin converting enzyme inhibitors; ARBs: angiotensin receptor blockers." (PMID 28700032, 2017). "Myocardial infarction was the predominant clinical diagnosis and all patients were NYHA class I. Pharmacologic treatment commonly included antiplatelets, statins, beta-blockers, ACE inhibitors, and hypoglycemic agents." (PMID 27556384, 2016). "This first clinical cardiovascular local RAS example relates to the introduction of angiotensin-converting enzyme (ACE) inhibitors and later to angiotensin II (type 1) receptor blocking agents (ARBs) to patients hospitalized with an initial myocardial infarction." (PMID 24600438, 2014). "Furthermore, they experienced more myocardial infarction and isolated CABG surgery and received more frequent other cardiovascular drug therapies, such as aspirin, beta-blockers and ACE-inhibitors." (PMID 25055990, 2014). "No immunoreactivity for ACE was found in ventricular myocytes from human control hearts, with ACE detected only in cardiomyocytes from hearts after myocardial infarction." (PMID 22518286, 2012). "This increased adverse event rate with ARB + ACE inhibitor with no efficacy benefit was also seen in the VALsartan In Acute myocardial iNfarcTion (VALIANT) trial with valsartan and captopril." (PMID 20920303, 2010). "In this study, they induced myocardial infarction (MI) by coronary artery ligation and observed an increase in Ang II, Ang 1-9, ACE2, and ACE levels after 1 week of MI, while only ACE2 and Ang 1-9 levels decreased after 8 weeks." (PMID 37959338, 2023). "Accordingly, chronic ACE inhibition did not repress Ang II levels in the cardiac interstitial fluid while combined chymase and ACE inhibition improved cardiac function, decreased adverse cardiac remodeling, and improved survival after myocardial infarction." (PMID 34220496, 2021). "As the most potent bioactive molecule involved in the classic angiotensin-converting enzyme-Angiotensin II-Angiotensin II type 1 receptor (ACE-AngII-AT1R) axis, AngII ensures the development of pathological cardiac remodeling upon myocardial infarction (MI)." (PMID 36167556, 2022). "The Heart Outcome Prevention Evaluation (HOPE) study assessed the effects of angiotensin-converting enzyme (ACE) inhibition and vitamin E on incident cardiovascular disease (CV death, stroke, and non-fatal myocardial infarction (MI))." (PMID 33396615, 2020).
myocardial infarction (continued). "If a patient has recently had a myocardial infarction...it pulls out your main groups of drugs from the NICE guidelines and flash up oh they’re not on an ACE inhibitor and you’ve got to say why." (PMID 41505743, 2026). "Consistent mortality reductions have been demonstrated on top of ACE inhibitor therapy (with or without additional beta blockade) in the setting of LVSD in both chronic heart failure and early following myocardial infarction." (PMID 24278681, 2012).
chronic kidney disease (360 papers, 2005 to 2026). Impairment of the renal function secondary to chronic kidney damage persisting for three or more months. "Evidences have shown that D allele of ACE I/D polymorphism was associated with increased risk of end-stage renal disease susceptibility, coronary artery disease in T2DM patients and early onset primary knee osteoarthritis in Asian Indian populations." (PMID 27758878, 2016). "The ACE I/D polymorphism alone, and haplotypes including this and other markers within the ACE gene, have been associated with DN progression and end stage renal disease in particular, which in turn leads to UN." (PMID 26074879, 2015). "Therapies with ACE inhibitors in patients with congestive heart failure or advanced chronic renal disease have demonstrated that is associated with a significant decrease in TNF-α and IL-6 activity." (PMID 25785280, 2015). "Associations between angiotensin-converting enzyme (ACE) gene insertion/deletion (I/D) polymorphisms and chronic kidney disease (CKD) have been extensively studied, with most studies reporting that individuals with the D allele have a higher risk." (PMID 24498151, 2014). "It has been advocated that the dual blockade approach of ACE inhibitors and ARBs theoretically should result in improved outcomes in both cardiovascular disease and chronic kidney disease which are usually associated with bone disturbances." (PMID 23971050, 2013). "Angiotensin I-converting enzyme gene insertion/deletion and angiotensinogen M235T polymorphisms: Risk of chronic renal failure." (PMID 23401650, 2013). "In the present study, we have investigated the association between ACE gene polymorphism and the causation of renal disease in 127 end stage renal disease patients from north India." (PMID 17042963, 2006). "Stratification analyses for microalbuminuria, macroalbuminuria and end-stage renal disease (ESRD) were also conducted for five variants: Ins/Del variant at ACE gene; SNP rs2268388 at ACACB gene; SNP rs1799987 at CCR5 gene; SNPs rs1800795 and rs1800796 at IL-6 gene." (PMID 40116328, 2025). "On the other hand, albuminuria could be reduced by ACE inhibitors and ARBs, which have been shown to delay progression to end-stage renal disease and reduce cardiovascular risk." (PMID 38541022, 2024). "In addition, chronic renal insufficiency associated with HF limits the use of treatments that modify the evolution of the disease, such as ACE inhibitors, ARABs, and antialdosteronics." (PMID 38068309, 2023). "Also, significant clinical predictors of all-cause mortality included female sex, age, BMI, NYHA class, chronic kidney disease, liver disease, atrial fibrillation, stroke, use of oral anticoagulants/ACE inhibitors or ARBs/diuretics, and LVEF." (PMID 35213653, 2022). "Therapeutic targeting of ACE and ET-1 may help decrease the risk for kidney injury in the developing neonate to prevent and/or treat neonatal acute kidney injury and/or chronic kidney disease." (PMID 34481475, 2021). "For these reasons, clinically used anti-hypertensive mainstay therapies that provide reno-protection and reduce the risk of progression to end-stage renal disease including angiotensin converting enzyme (ACE) inhibitors and angiotensin receptor blockers (ARBs) were developed." (PMID 35197849, 2021). "Furthermore, the D allele has been linked to a failure of the renoprotective action of ACE inhibitors to retard the development of end stage renal disease (ESRD)." (PMID 17042963, 2006). "The association between angiotensin-converting enzyme insertion/deletion (ACE I/D) polymorphisms and plasma ACE levels may allow for the optimization of a preventive intervention to reduce cardiovascular morbidity and mortality in the chronic kidney disease (CKD) population." (PMID 35885904, 2022).